STAT3 (signal transducer and activator of transcription 3)
Diseases named in the same sentence as STAT3 in open-access papers (continued):
Sharing a sentence is not in itself a finding about the gene and the disease.
cancer (continued). "Phosphorylated STAT3 then translocates to the nucleus, promoting the transcription of genes related to cancer progression." (PMID 39791716, 2024). "According to reports, the FAK/STAT3 signaling mechanism is important for cancer cells’ movement, invasion, and survivability." (PMID 39588118, 2024). "A pivotal mechanism underlying this enhancement involves the activation of the STAT3 signaling pathway by S1PR1, thereby fostering cancer initiation, growth, and dissemination." (PMID 39551792, 2024). "As a novel SPOP substrate, STAT3 drives a battery of genes involved in cancer stemness maintenance, including SOX2." (PMID 39479456, 2024). "M1 macrophages can inhibit tumor growth, while M2 macrophages can enhance the proliferation of cancer stem cells through the IL-6-induced activation of STAT3." (PMID 39684895, 2024). "STAT3 serves as the convergence point of multiple cancer-related pathways and is frequently overactivated in cancer progression." (PMID 38183097, 2024). "Our RNA-seq data revealed that KLF7 is linked with several cancer signaling pathways, such as PI3K/AKT, JAK/STAT3, and MAPK/ERK in COAD." (PMID 38164176, 2024). "EMT is a critical phase in the early stages of cancer metastasis and is controlled by signaling pathways such as STAT3 and Smad2/3." (PMID 39768811, 2024). "For instance, in our previous studies, we carried out ML-based virtual screening for the identification of new inhibitors against STAT3 a cancer drug target, and the Main protease drug target in the SARS CoV-2." (PMID 38528576, 2024). "Numerous studies have documented that the activation of STAT3 in cancer cells orchestrates the release of various pro-inflammatory cytokines, including IL-6, IL-10, and VEGF." (PMID 39468431, 2024). "The quiescence and activation of cancer cells involve a variety of intracellular signaling pathways, including the Stat3 and Akt signaling pathway." (PMID 38630320, 2024). "The effect of inhibiting STAT3 expression on the metastatic phenotype of cancer cell lines was investigated using trans-well migration." (PMID 39200368, 2024). "Another possible strategy for utilizing the lipid properties mediated by STAT3 for therapeutic purposes is to differentiate between cancer cells and normal cells, which often have minimal STAT3 activity." (PMID 38933330, 2024). "Another signalling pathway playing a significant role in cancer progression is STAT-3, which regulates numerous cellular processes such as the cell cycle, cell proliferation, cellular apoptosis, and tumorigenesis." (PMID 39203892, 2024). "Through its regulatory influence on the STAT3 pathway, PIAS emerges as a potential therapeutic target for addressing STAT3-dependent cancers." (PMID 38590645, 2024). "Targeted mechanisms of STAT3 involvement in cancer pathology include immunosuppression and promotion of stemness." (PMID 39272915, 2024). "Studying the oncogenic activity of STAT3 in various cancers provides opportunities for leveraging the STAT3 signaling pathway as a key therapeutic target in cancer treatment." (PMID 38339245, 2024). "By downregulating pro-inflammatory pathways, like NF-κB and STAT3, RA demonstrates potential in preventing cancer progression while mitigating oxidative damage through its antioxidant effects." (PMID 39594455, 2024). "We observed similar correlations in CESC, GBM, HNSC, and STAD cancers, where a strong association between CD59 and TAM is linked to worse prognosis through IL10/STAT3-dependent pathways." (PMID 39518137, 2024). "Here, CAF-derived IL6 triggered JAK/STAT3 activation in cancer cells, resulting in NOX4 upregulation." (PMID 38453816, 2024). "In contrast to SGC-CK2-1 and CX-4945, AB668 also induced a dose-dependent inhibition of the activated forms of STAT3, a protein that regulates proliferation and apoptosis in cancer cells." (PMID 38318383, 2024). "In a nutshell, curcumin inhibits JAK-STAT signaling through activation of PIAS3, thus decreasing STAT3 phosphorylation and cancer cell growth." (PMID 38590645, 2024).
cancer (continued). "In a colitis-associated carcinoma mouse model, IL-22 induced epithelial signal transducer and activator of transcription 3 (STAT-3) phosphorylation and proliferation, thereby facilitating cancer development." (PMID 39309440, 2024). "As a consequence of regulating multiple signaling pathways crucial for cancer progression, STAT3 has been considered as an attractive therapeutic target." (PMID 39305962, 2024). "Immune cell function can also be modulated by cancer-derived exosomes containing STAT3 activating cargo." (PMID 39200368, 2024). "AKT1 kinase has been found to enhance the inhibitory function of MDSCs in cancer and inflammation; in this investigation, p-STAT3 and p-AKT were activated." (PMID 39609883, 2024). "Nicotine enhances α7-nACh receptor expression and promotes the M2-type polarisation of microglia by disrupting EGFR signalling and STAT3 pathways, thus promoting cancer cell progression and metastasis." (PMID 39364322, 2024). "Interleukin-6 (IL-6), a pro-inflammatory cytokine, facilitates cancer development by activating the Janus kinase 2 (JAK2)–signal transducer and activator of transcription 3 (STAT3) pathways." (PMID 38672257, 2024). "Researchers viewed STAT3 as a primary target for cancer therapy because of its crucial involvement in cancer formation." (PMID 38397437, 2024). "JAK2/STAT3 signaling has been widely implicated in mitochondria-dependent apoptosis and cancer metastasis, thus attracted our attentions and western blotting was applied to compare JAK2/STAT3 pathway activity in PTPRO-overexpressing and control groups." (PMID 38182570, 2024). "Toll-like receptors (TLRs) such as TLR2, TLR3, TLR4, TLR7, TLR9 are expressed on various immune cells, epithelial and stromal compartments and function in STAT3 mediated cancer development and progression." (PMID 38245798, 2024). "Inhibiting the STAT3 signalling pathway has been elucidated to impede cancer progression and enhance the efficacy of chemotherapy‐induced cell death." (PMID 38661644, 2024). "One notable example is Napabucasin (BBI608), a first-in-class cancer stemness inhibitor that suppresses cancer stemness by targeting STAT3-driven gene transcription." (PMID 38981878, 2024). "Stattic has been shown to induce apoptosis in STAT3-dependent cancer cell lines, which selectively inhibits the activation, dimerization and nuclear translocation of STAT3." (PMID 39000312, 2024). "For example, as with the PRLR mediated activation of STAT3, targeting this upstream regulator of the pathway provides a promising outlook on treating patients with various cancers including PDAC." (PMID 38464736, 2024). "By inhibiting STAT3 signaling, the metastatic potential is reduced, and cell adhesion properties are increased, ultimately inhibiting cancer cell migration and invasion." (PMID 39519023, 2024). "AM-18002 treatment was found to inhibit the expansion of myeloid-derived suppressor cells (MDSC), cancer cell migration and invasion, and STAT3 phosphorylation." (PMID 38625901, 2024). "Although STAT3 and STAT5 are the STAT family members most widely associated with cancer pathogenesis, other STATs can become activated inappropriately in cancer cells and play important biological roles." (PMID 38611065, 2024). "For instance, IL-6 has been shown to activate cancer stem cells, facilitating cancer growth and metastasis by promoting anti-apoptotic pathways through STAT3 phosphorylation." (PMID 38840908, 2024). "The activation of the Jak2/Stat3 signaling pathway is a key factor in the occurrence of various malignant tumors." (PMID 39203920, 2024). "Interference with vital cellular signaling pathways (e.g., Wnt/β-catenin, Notch, STAT3, mTOR, or NF-κB) was also documented for niclosamide and structurally related salicylanilides in various cancers." (PMID 39062194, 2024).
cancer (continued). "STAT3 inactivation triggered by sorafenib has been shown to elicit different types of cancer cell death including apoptosis and autophagy, possible via myeloid cell leukemia-1 (MCL1) downregulation." (PMID 38485916, 2024). "In conclusion, targeting the STAT3 and NF-κB signaling pathways using chalcones represents a promising cancer prevention and treatment approach." (PMID 38539427, 2024). "We identified IL-6 as a novel target of ERO1α and confirmed the suggestion by previous studies conducted using other cancer cell models that STAT3 directly transcriptional regulates SLC7A11." (PMID 38610018, 2024). "Overall, this review sheds light on the intricate relationships between inflammation and cancer, emphasizing the importance of the STAT3 gene and its activation in the pathophysiology of these conditions." (PMID 38238319, 2024). "Various chalcone molecules targeting the JAK2/STAT3 axis, such as licochalcone, butein, isoliquiritigenin, 4,3′,4′,5′- tetramethoxychalcone, and Llicochalcone, have been utilized in cancer intervention." (PMID 38686052, 2024). "It promotes cancer progression and growth by stabilizing the transcription factor signal transducer and activator of transcription 3 (STAT3)." (PMID 38328550, 2024). "For instance, Celecoxib inhibits cancer cell proliferation and migration by down-regulating both the expression and phosphorylation of STAT3, thereby enhancing the radiosensitivity of cancer stem cells." (PMID 39598398, 2024). "STAT3 can directly couple with NF-κB, and both molecules cooperatively can modulate the expression of several genes involved in cancer invasiveness and metastasis, including resistance to apoptosis." (PMID 37789138, 2024). "STAT3 is excessively active in numerous cancer types and has demonstrated to be a significant route in the propagation of cancer mediated by CSCs." (PMID 39204369, 2024). "The phosphorylated STAT3 continues to activate downstream effectors and signal pathways for the proliferation and apoptosis of cancer cells." (PMID 39174877, 2024). "Considering the importance of the IL6/GP130/STAT3 signaling pathway in tumorigenesis and progression, targeting this pathway is a promising approach to cancer treatment." (PMID 39152779, 2024). "Stat3 is a critical transcription factor in mammals that is involved in the progression of many cancers, such as NSCLC." (PMID 39085849, 2024). "In both normal and cancer cells, the transcription factor STAT3 plays an essential role in a number of signal transduction pathways." (PMID 39204369, 2024). "What is the specific role of the STAT3/miR-34a/IL-6R loop when activated in cancer cell lines with multiple mesenchymal phenotypes?" (PMID 38172648, 2024). "It is reported that the increased production of ATP accelerates the proliferation of cancer cells, which is strongly controlled by STAT3 activation." (PMID 39273033, 2024). "Ideally, this approach would incorporate serial monitoring through duration of therapy in order to identify a subset of cancer patients who will benefit from prolonged STAT3 inhibition." (PMID 38339245, 2024). "The modulatory effect of STAT3 on FoxP3 expression has been reported on Tregs infiltration in cancer." (PMID 39150932, 2024). "BDNF activates tropomyosin-related receptor kinase B (TrkB), initiating critical signaling pathways such as RAS/MAPK, PI3K/Akt, and JAK2/STAT3, which influence cancer progression and affect cellular processes including proliferation and migration." (PMID 39401197, 2024). "In NSCLC, the promotion of angiogenesis occurs through interleukin‐17, which stimulates the production of VEGF in cancer cells via the STAT3/GIV signaling pathway." (PMID 38491831, 2024). "RKIP also has activities with other key hallmarks of cancer, such as the inhibition of the signal transducer and activator of transcription 3, STAT3." (PMID 38786085, 2024).
cancer (continued). "The article also thoroughly summarizes the inhibition of STAT3 signaling by certain terpenoid phytochemicals, which have demonstrated strong efficacy in several preclinical cancer models." (PMID 38397437, 2024). "Observing the induction of apoptosis in pancreatic cell lines and its strong affinity to STAT3, panaxadiol offers useful insights into the role of STAT3 in cancer proliferation and metastasis through its inhibition." (PMID 38464736, 2024). "Signal transducer and activator of transcription 3 (STAT3) hyperactivation can disarm DCs and subvert the protective immune surveillance of cancers." (PMID 38523840, 2024). "Subsequently, the attention was directed towards STAT3, given its implication in the development of numerous forms of cancers in humans." (PMID 38238515, 2024). "Our findings also elucidate the mechanism behind anlotinib’s effectiveness, highlighting its role in inhibiting the JAK2/STAT3 pathway, a key regulator in cancer progression." (PMID 39508048, 2024). "Our previous study demonstrated that caspases activation leads to the persistence of spontaneous DBS in cancer cells, which then activates NF-κB and STAT3 to maintain or enhance tumorigenicity and cancer cell stemness." (PMID 38977663, 2024). "Our data may also help further dissecting the well-known pro-oncogenic roles of STAT3, suggesting that aberrant, ectopic activation of Lncenc1 and perhaps other pluripotency-associated non-coding STAT3 target RNAs may contribute to the acquisition of cancer stem cell features." (PMID 37801430, 2024). "Compared with FGFR4-Gly388 patients, FGFR4-Arg388 patients were more likely to have a higher cancer stage, poorer survival, and significantly higher levels of wave proteins (p = 0.025) and p-STAT3 (p = 0.009)." (PMID 39309860, 2024). "According to reports, elevated levels of LINC00518 promote cancer progression by activating the JAK/STAT3 signaling pathway." (PMID 39108268, 2024). "For instance, approaches aimed at reversing the immunosuppressive TME, addressing the metabolic adaptations in cancer cells, or inhibit the pro-tumorigenic effects regulated by STAT3." (PMID 39468431, 2024). "Combined administration of both PI3K and STAT3 inhibitors achieved a long-term cancer elimination in vitro and in vivo, highlighting their therapeutic potential for BCa treatment." (PMID 39068158, 2024). "STAT3 has been recognized as the canonical downstream signaling of IGF1R, and the IGF1R/STAT3 signaling axis has been associated with the development of cancer chemoresistance." (PMID 39394189, 2024). "Methylation of SOCS1, another member of the SOCS family, has been shown to be hypermethylated and contribute to STAT3 activation in MM, a cancer that shares several similarities with PEL." (PMID 38534772, 2024). "An additional investigation revealed a correlation between the constitutive activation level of STAT3 and the cancer cell’s ability to withstand doxorubicin-induced apoptosis." (PMID 38397437, 2024). "Activation of STAT3 in cancer cells leads to proliferation and suppression of apoptosis and we can observe that in BC where STAT3 is activated by elevated levels of IL-6 and IL-10." (PMID 38892394, 2024). "Unphosphorylated STAT3 (here mimicked as Y705F) is relevant for a number of newly found roles in cancer, but the role of additional PTMs in its function is barely understood." (PMID 38150153, 2024). "The inhibition of STAT3 not only reversed the unfavorable effect of LDHC silencing in the Her2-enriched cancer cells but also demonstrated significant anti-cancer activity when used as a single agent." (PMID 39001513, 2024). "In metastasis, NF-κB cooperates with STAT3 in promoting cancer progression, conferring resistance to apoptosis and plasticity." (PMID 39061137, 2024).
cancer (continued). "It has been reported that STAT3 plays a crucial role in various types of cancers, activation of STAT3 leads to increased tumorigenic ability and the transition of cancer stem cells (CSCs) in cancer via enhancing the epithelial-mesenchymal transition (EMT)." (PMID 39068158, 2024). "In oncogene-addicted cancers, a positive feedback look that promotes STAT3 activation induces resistance to targeted therapy." (PMID 38480916, 2024). "Activation of STAT3 by JAK leads to transcriptional induction of the JAK inhibitor SOCS3 by STAT323, suggesting that STAT3 activity can oscillate in JAK-activated cancer cells and EGFR-mutated cancer cells." (PMID 38760429, 2024). "STAT3 mediates the Warburg effect by enhancing aerobic glycolysis and reducing oxidative phosphorylation even in the presence of oxygen in several cancer types." (PMID 38245798, 2024). "It has long been established that NF-κB and STAT3 signaling are closely intertwined and that they collaborate in a variety of pathological processes, with cancer being a notable example." (PMID 38856747, 2024). "Many studies show that EGFR activates MAPK and JAKs-STAT3 signaling pathways, and STAT3 is involved in the survival of cancer stem cells (CSCs)." (PMID 39136000, 2024). "This was confirmed by evaluating the activation of STAT3 and gene expression of GM-CSF in carcinoma cells exposed to CAF-conditioned media (CAF-CM)." (PMID 39199680, 2024). "Given the fact that STAT3 phosphorylation remains a prognostic marker for EMT in various carcinomas, we needed to determine the location and expression status of this molecule in the tongues during the carcinogenic process." (PMID 38585261, 2024). "Chalcones have emerged as potential molecular therapeutics against malignant carcinomas via modulation JAK2/STAT3 signaling pathway." (PMID 38686052, 2024). "Aggressive carcinomas develop only in the presence of additional mutations, such as abnormal expression of ERG, loss of IL-6/STAT3 functionality, dysfunction of the methyltransferase Kmt2c or activation of the RAS/MAPK cascade." (PMID 38811984, 2024). "Constitutive activation of STATs, in particular STAT3, is found in carcinoma from the head and neck, lung, breast, ovary, and prostate." (PMID 38916963, 2024). "For example, silencing the PPP enzyme glucose-6-phosphate dehydrogenase (G6PD) reduces cancer cell proliferation and migration by inhibiting STAT3 and epithelial-to-mesenchymal transition (EMT) formation." (PMID 37762231, 2023). "Signal transducer and activator of transcription 3 (STAT3)-a core regulator of the STAT family that is overexpressed in various cancers including NSCLC-has become an attractive molecular target for cancer therapy." (PMID 37928418, 2023). "IL-6 signaling and its downstream player STAT3 are strongly involved in the crosstalk between cancer and stroma cells." (PMID 36639824, 2023). "IL-6, an inflammatory tumor cytokine, activates a series of downstream factors by activating the IL-6/STAT3 signaling pathway, which plays a significant role in the growth and development of many human cancers." (PMID 36769245, 2023). "By analyzing the associations between sunitinib sensitivity and the activity of STAT3 signaling using the Cancer Therapeutics Response Portal, we found that STAT3 signaling was significantly activated in cells with a higher IC50 of sunitinib." (PMID 36720918, 2023). "Under normal conditions the duration of STAT3 activity is short and transient but in pathological situations, such as cancer, a stronger activation is maintained over long periods of time." (PMID 36902166, 2023). "As such, these compounds show promise as potential drugs for treating certain cancers through the inhibition of STAT3, though more studies are needed to determine its effectiveness in treating OvCa." (PMID 37173951, 2023).